RASA2 (RAS p21 protein activator 2)
Description:
Inhibitory regulator of the Ras-cyclic AMP pathway. Binds inositol tetrakisphosphate (IP4).
Synonyms: GAP1m
Tractability: PROTAC: ubiquitination databases record sites on it; its protein half-life has been measured.
Gene: Protein-coding gene on chromosome 3 (141,486,967 to 141,615,345, forward strand). Ensembl gene ENSG00000155903.
Subcellular location: Cytoplasm; Cytoplasm, perinuclear region
Subcellular location (Human Protein Atlas): Vesicles
Pathways (Reactome):
Signal Transduction: Regulation of RAS by GAPs
Gene Ontology:
Molecular function: protein binding; GTPase activator activity; phospholipid binding
Biological process: regulation of intracellular signal transduction; signal transduction; intracellular signal transduction; negative regulation of Ras protein signal transduction
Cellular component: cytosol; cytoplasm; perinuclear region of cytoplasm
Genetic constraint (gnomAD): Loss-of-function variants: 88 observed, 70.82 expected, observed/expected ratio (o/e) 1.24, 90% interval 1.04 to 1.48. The upper end of that interval is the gene's LOEUF score, 1.48, which puts it in group 6 of 6, group 1 being the genes least tolerant of losing a copy. Missense variants: 820 observed, 771.22 expected, observed/expected ratio (o/e) 1.06, 90% interval 1 to 1.13. Synonymous variants: 298 observed, 273.19 expected, observed/expected ratio (o/e) 1.09, 90% interval 0.99 to 1.2.
Gene-disease validity (ClinGen):
ClinGen rates the evidence that RASA2 causes each of these diseases.
Noonan syndrome (autosomal dominant): Limited. Noonan Syndrome (NS) is characterized by short stature, typical facial dysmorphism and congenital heart defects.
Homologues: Orthologues: chimpanzee RASA2 (99% identical), macaque RASA2 (99% identical), pig RASA2 (98% identical), dog RASA2 (97% identical), guinea pig RASA2 (96% identical), rabbit RASA2 (93% identical), mouse Rasa2 (89% identical), rat Rasa2 (86% identical), tropical clawed frog rasa2 (75% identical), zebrafish RASA2 (61% identical), Drosophila melanogaster RasGAP1 (38% identical), Drosophila melanogaster raskol (20% identical), and 2 more. Paralogues in human: RASA3 (59% identical), RASA4 (28% identical), RASA4B (28% identical), NF1 (27% identical), RASAL1 (26% identical), DAB2IP (19% identical), RASA1 (18% identical), RASAL2 (18% identical), RASAL3 (14% identical).
Diseases named in the same sentence as RASA2 in open-access papers:
RASA2 is named in the same sentence as 34 diseases in open-access papers, as found by Europe PMC text mining. Sharing a sentence is not in itself a finding about the gene and the disease. The quoted sentences say what the papers report.
melanoma (12 papers, 2016 to 2025). A malignant, usually aggressive tumor composed of atypical, neoplastic melanocytes. "Recently, RASA2 and NRAS mutations were confirmed to be mutually exclusive, with NF1 mutations significantly co-occurring with RASA2 mutations in BRAF and NRAS wild-type melanomas, since RASA2 inhibits NRAS and NF1 inhibits KRAS and HRAS." (PMID 32850962, 2020). "A concern might be that RASA2 loss-of-function mutations, although uncommon, have been implicated in a subset of cancers, most prominently melanoma and multiple myeloma." (PMID 36002574, 2022). "Similarly, RASA2 gene alterations co-occur with NF1 mutation in melanoma, where RASA2 is mutated in about 5% of patients, leading to Ras signaling activation." (PMID 33096593, 2020). "In addition, all 26 NF1 mutant BRAF-RAS wild-type melanomas carried mutations in other known RASopathy genes, including RASA2, PTPN11, SOS1, RAF1 and SPRED1." (PMID 28637487, 2017). "The RAS p21 protein activator 2 (RASA2) gene identified in our study encodes a protein that has been previously demonstrated to serve as a tumor suppressor in melanoma, and therefore, mutations affecting RASA2 might be associated with uncontrolled inflammation." (PMID 38892353, 2024). "NF1-mutant melanomas preferentially harbored alterations in RASopathy genes, with SPRED1, RASA2, and RASSF2 being identified as significantly mutated genes within the subtype." (PMID 38758740, 2024). "For example, the recurrent inactivation of RASA2 in melanoma favors constitutive activation of Ras signaling, and the frequent downregulation of RASA4 in myelomonocytic leukemia correlates with poor prognosis and higher risk of relapse after therapy." (PMID 33096593, 2020). "Furthermore, loss-of-function mutations of RASA2 have been linked to increased RAS activation, melanoma cell growth, and migration in melanomas." (PMID 40361412, 2025). "RASA2 mutations co-occurred in NF1 mutant melanomas that were BRAF-RAS wild type, in a WES study of 213 melanoma samples (62 cell lines and 151 melanomas); 12.2% (26/212) of melanomas were NF1-mutant/BRAF-RAS-wild-type and nine of them harbored co-mutations in RASA2 (2 nonsense and 3 R551C)." (PMID 32850962, 2020). "But, whilst mutant NF1 is known to cooperate with RASopathy genes (RASA2, PTPN11, SOS1, RAF1 and SPRED1) in melanoma and although NF1 is found to be frequently mutated (25–30%) in melanomas harbouring wild-type BRAF and NRAS, it is curious that melanoma is not a tumour type associated with NF1." (PMID 28637487, 2017). "Indeed, RASA2- and NF1-mutated genes co-selection in melanoma could be equivalent to oncogenic RAS mutation." (PMID 32850962, 2020). "Tumor suppressive function of NF1 (neurofibromatosis type 1) in several cancer types including melanoma, DAB2IP in prostate cancer, RASAL2 in breast cancer, PLXNC1 (Plexin C1) and RASA2 in melanoma have been described." (PMID 26993606, 2016). "Importantly, another RAS-GAP, Ras GTPase-activating protein 2 (RASA2), is inactivated in a significant proportion of melanoma." (PMID 35234863, 2022). "Furthermore, the inactivation of RASA2 activates the RAS signaling and favor the malignant phenotypes of melanoma cells." (PMID 34752201, 2021). "Although previous studies demonstrated RASA2 inactivation as a driver of several cancers including melanoma and Sézary Syndrome, no published studies have reported its association with breast cancer." (PMID 29228687, 2017).
RASopathy (7 papers, 2017 to 2025). Developmental syndromes caused by germline mutations (or in rare cases by somatic mosaicism) in genes that alter the Ras subfamily and mitogen-activated protein kinases that control signal transduction. "Herein, we confirmed that mutations in the RASopathy genes RASA2 and PTPN11 were enriched in the NF1 subtype and also identified RASSF2, a RAS domain‐containing gene, as enriched in the NF1 subtype." (PMID 28267273, 2017). "We focused on RASA2 (RAS p21 protein activator 2), a gene recurrently mutated by loss-of-function mutations in the RASopathy Noonan syndrome, and in a number of other malignancies, as all 4 guides scored in our screen for the CMS cell line and one for WSU-AML." (PMID 40470252, 2025). "The patient with the high mutational burden had a RASopathy profile, showing a NF1 mutation, together with truncation of RASA2, leading to increased activation of Ras." (PMID 31500314, 2019). "Searching for co‐occurring mutated genes revealed the RASopathy genes PTPN11 and RASA2, as well as another RAS domain‐containing gene RASSF2 enriched in the NF1 subtype after adjustment for mutational burden." (PMID 28267273, 2017). "Interestingly, one patient showed a RASopathy profile with NF1 truncation and mutations in RASopathy genes like RASA1 and RASA2, which is known from cutaneous melanoma." (PMID 31500314, 2019).
Noonan syndrome (5 papers, 2018 to 2025). "Rare variants in RASA2 have been found associated with Noonan syndrome." (PMID 34440387, 2021). "As scoliosis occurs frequently in Noonan syndrome, RASA2 is a potential candidate gene for CS." (PMID 34440387, 2021).
cutaneous melanoma (4 papers, 2017 to 2025). A primary melanoma arising from atypical melanocytes in the skin. "Overall, frequency of RASA2 mutations and CNVs in our skin melanomas dataset is 5.5 and 1%, respectively." (PMID 32850962, 2020). "NF1 mutations are present in 5% of BRAF-, 13% of NRAS-, and 50% of RASA2-mutant cutaneous melanomas." (PMID 39804140, 2025). "The K81Q mutation was the only RASA2 mutation present in the TCGA-UVM dataset, so its co-occurrence with NF1 copy-number loss is quite interesting, given the previously observed co-occurrence of RASA2 and NF1 mutations in cutaneous melanomas." (PMID 39804140, 2025).
asthma (3 papers, 2018 to 2022). "Three of the four identified genes, TBC1D16, TBC1D8, and RASA2, have been previously implicated in relation to asthma and/or obesity/BMI, supporting the informativity of genes identified in this study." (PMID 34301314, 2021). "Many studies have suggested a connection between RASA2 and BMI, as well as its association with atopy and asthma." (PMID 34301314, 2021).
Obesity (3 papers, 2017 to 2026). Accumulation of substantial excess body fat. "This study provided a novel insight into the roles of obesity and gene polymorphisms of RASA2, CADM1 and HIF1AN in the development of breast cancer." (PMID 29228687, 2017). "Such risk might be modified by specific polymorphisms of obesity-related genes such as RASA2 rs16851483, CADM1 rs12286929 and HIF1AN rs17094222, yielding some novel insights into breast carcinogenesis." (PMID 29228687, 2017). "In this study, we investigated the association of three polymorphic sites, RASA2 (rs16851483), CADM1 (rs12286929) and HIF1AN (rs17094222), with breast cancer risk among Chinese women based on previously identified obesity-related SNPs from the GWAS study." (PMID 29228687, 2017). "Genome-wide association studies (GWAS) have indicated that gene polymorphisms in alleles of RAS p21 protein activator 2 (RASA2), cell adhesion molecule 1 (CADM1) and hypoxia inducible factor 1 alpha subunit inhibitor (HIF1AN) are associated with the risk of obesity." (PMID 29228687, 2017).
breast carcinoma (2 papers, 2017 to 2023). "After adjusting for potential confounders, the T/T genotype of RASA2 (rs16851483) was associated with an increased risk of breast cancer compared with the G/G genotype (OR = 1.68, 95%CI: 1.10–2.56)." (PMID 29228687, 2017). "Our results showed that the mutant T/T genotype of RASA2 (rs16851483) was associated with an increased risk of breast cancer, and this finding was more pronounced in postmenopausal women." (PMID 29228687, 2017). "Women carrying RASA2 (rs16851483) T/T genotype and BMI ≥ 24 were under a higher risk of breast cancer compared with those who had the G/G genotype and BMI < 24 (OR = 2.51, 95% CI: 1.38–4.56), revealing an additive interaction between specific genotype and BMI." (PMID 29228687, 2017). "Stratifying analyses by menopausal status indicated that RASA2 T/T genotype significantly enhanced breast cancer risk among postmenopausal women (OR = 1.80, 95%CI: 1.05–3.09)." (PMID 29228687, 2017). "Whether this polymorphism of RASA2 gene influenced intracellular protein function to promote the development of breast cancer depends on further investigation in the near future." (PMID 29228687, 2017). "Meanwhile, we also observed significant interaction between RASA2 genotypes and high body fatness for breast cancer susceptibility, suggesting that the specific genotype of RASA2 could modify the risk of breast cancer induced by high body fatness." (PMID 29228687, 2017). "In this study, we explored the interactions between candidate SNPs of RASA2 (rs16851483), CADM1 (rs12286929) and HIF1AN (rs17094222) and body fatness for breast cancer risk." (PMID 29228687, 2017). "Results showed that the T/T genotype of RASA2 (rs16851483) was associated with increased breast cancer risk, and the G/A genotype of CADM1 (rs12286929) might play a role in reducing the risk of breast cancer." (PMID 29228687, 2017).
diabetes (1 paper, 2025). "In a GWAS study of the Taiwan Biobank (TWB), four novel genes—NABP2, RASA2, RNF41, and SLC39A5—were identified for human height, and it was also discovered that these genes have associated with cardiovascular disease, diabetes, and cancer." (PMID 39910149, 2025).
head and neck cancer (1 paper, 2016). A primary or metastatic malignant neoplasm affecting the head and neck.
hypothyroidism (1 paper, 2020). Abnormally low levels of thyroid hormone. "At a gene level, PTPN11, NRAS, RASA2, SOS2, MAP2K1, and RAF1 were significantly associated with hypothyroidism, diastolic and systolic BP, birth weight, growth abnormality, subcutaneous adipose tissue, standing/sitting height ratio and body mass index." (PMID 33226994, 2020).
leukaemia (1 paper, 2022). "In this leukaemia model, RASA2-deficient TCR T cells also improved tumour control." (PMID 36002574, 2022). "RASA2-knockout CAR T cells had a competitive fitness advantage over control cells in the bone marrow in a mouse model of leukaemia." (PMID 36002574, 2022). "The persistence advantage we observed in the bone marrow as well as in the repeated cancer cell killing assays in vitro led us to test whether RASA2 KO confers an advantage to CAR T cells in controlling repeated leukemia injections in vivo." (PMID 36002574, 2022). "In addition, to assess tumour-antigen-stimulated T cells, we treated an additional cohort of mice bearing Nalm6 leukaemia with control and RASA2-KO CD19 TRAC CAR T cells to achieve tumour clearance and observed these mice to 116 days after CAR T cell injections." (PMID 36002574, 2022). "Whereas both RASA2-KO and control CAR T cells efficiently killed leukaemia cells expressing high CD19 levels, RASA2 inactivation augmented the in vitro killing of leukaemia target cells versus control T cells in the context of low antigen expression." (PMID 36002574, 2022). "To test whether RASA2 ablation in TCR T cells could improve control of a liquid tumour bearing the same NY-ESO-1 antigen, we injected Nalm6 leukaemia cells engineered to express NY-ESO-1 on cognate major histocompatibility complex class I molecules (MHCI) into the tail vein of mice." (PMID 36002574, 2022).
neurofibroma (1 paper, 2024). An intraneural or extraneural neoplasm arising from nerve tissues and neural sheaths. "Thus, to further validate CRISPRi screen results, we directly tested 2 of the top sgRNAs that were enriched after selumetinib treatment (T10/T0), RASA2 or KEAP1, which were suppressed in NF1-mutant, PRC2-intact neurofibroma cells using 2 independent sgRNA protospacer sequences." (PMID 38216572, 2024).
prostate carcinoma (1 paper, 2016). A carcinoma that arises from epithelial cells of the prostate gland.
scoliosis (1 paper, 2021). A congenital or acquired spinal deformity characterized by lateral curvature of the spine. "Some candidates, such as DHX40, NBPF20, RASA2, and MYSM1, have been found to be associated with syndromes with scoliosis or implicated in bone/spine development." (PMID 34440387, 2021).
venous thromboembolic disease (1 paper, 2022). "For example, the Pitta Kapha replicated profile GWAS SNPs in RASA2, ADK and CTU1 have an association with immuno-metabolic traits and diseases, blood and coagulation related traits/diseases such as venous thromboembolic disease." (PMID 35330488, 2022).
tumor (9 papers, 2016 to 2026). "Transfer of RASA2-deficient T cells significantly slowed tumour growth and improved survival compared with mice that received control-edited T cells." (PMID 36002574, 2022). "This reduced tumour burden resulted in significantly prolonged survival of the mice that received RASA2-deficient TRAC CAR T cells." (PMID 36002574, 2022). "Repeated tumour antigen stimulations in vitro revealed that RASA2-deficient T cells show increased activation, cytokine production and metabolic activity compared with control cells, and show a marked advantage in persistent cancer cell killing." (PMID 36002574, 2022). "Whereas RASA2-deficient effector T cells maintained their robust cytotoxic function, control T cells were unable to control tumour cell growth in the presence of suppressive Treg cells." (PMID 36002574, 2022). "Nonetheless, we found that the RASA2-deficient TRAC CAR T cells had a marked advantage over control TRAC CAR T cells in tumour control, as measured by bioluminescence imaging in cohorts of mice treated with cells from multiple different human blood donors." (PMID 36002574, 2022). "However, it is notable that RASA2 is usually co-mutated with other tumor suppressors (such as NF-1), suggesting reduced transformation potential as a single mutation." (PMID 36002574, 2022). "Here we used such a screening platform to model a variety of tumour-relevant suppressive conditions and found that these screens converged on RASA2 as a promising candidate target for engineering resistance to multiple inhibitory signals." (PMID 36002574, 2022). "Genome-wide CRISPR screens, biochemical studies and animal models show that RASA2 has a key role in regulating T cell function and has potential as a genetic target for enhancing anti-tumour immunity." (PMID 36002574, 2022). "For instance, RASA2 ablation limited the observed decline in T cell viability seen with repeated tumour exposures." (PMID 36002574, 2022). "Here we describe unbiased genetic screens performed under several immunosuppressive conditions commonly encountered in the tumour microenvironment (TME) that uncovered ablation of the RASA2 gene as a strategy for T cells to overcome multiple inhibitory cues." (PMID 36002574, 2022). "RNA-seq analysis of RASA2 expression in repetitively stimulated T cells showed that although RASA2 levels declined after acute stimulation, they increased upon repeated tumour exposures." (PMID 36002574, 2022). "Published scRNA-seq datasets from human patients also revealed higher RASA2 levels in tumour-infiltrating T cells compared with peripheral T cells, suggesting a potential role for RASA2 in dampening T cell responsiveness in the TME." (PMID 36002574, 2022). "We found that RASA2-KO CAR T cells had an advantage over control CAR T cells in reducing tumour burden and increasing survival in this tumour-rechallenge model, demonstrating that RASA2 ablation can improve functional persistence in vivo." (PMID 36002574, 2022). "Ablation of negative regulators that hinder TCR response in T cells not only promoted T cell activation but significantly enhanced T cell tumour-killing capabilities through pathways of MAPK (RASA2), ubiquitination degradation (CBLB), and JAK/STAT (SOCS1 and TCEB1)." (PMID 38581063, 2024). "Bioluminescence measurements of tumour burden revealed that ablation of RASA2 in CAR T cells could significantly slow tumour growth and prolong survival compared with control CAR T cells in this model." (PMID 36002574, 2022). "Finally, we show that RASA2-ablation in antigen-specific T cells can enhance tumour control and extend survival in multiple preclinical models of liquid and solid tumours." (PMID 36002574, 2022). "We next tested whether ablation of RASA2, which we found to be upregulated in tumor-infiltrating T cells, would ameliorate chronic antigen-exposure-induced T cell dysfunction." (PMID 36002574, 2022).